OR6C1 (olfactory receptor family 6 subfamily C member 1)
Description:
Odorant receptor.
Synonyms: OST267
Tractability: Antibody: UniProt places it where antibodies can reach, with medium confidence; UniProt predicts a signal peptide or a membrane-spanning region; its Gene Ontology location is reachable by antibodies, with medium confidence.
Gene: Protein-coding gene on chromosome 12 (55,314,343 to 55,322,364, forward strand). Ensembl gene ENSG00000205330.
Subcellular location: Cell membrane
Pathways (Reactome):
Sensory Perception: Expression and translocation of olfactory receptors
Gene Ontology:
Molecular function: protein binding; olfactory receptor activity; G protein-coupled receptor activity
Biological process: detection of chemical stimulus involved in sensory perception of smell; G protein-coupled receptor signaling pathway
Cellular component: plasma membrane; membrane
Genetic constraint (gnomAD): Loss-of-function variants: 0 observed, 0.0767 expected, observed/expected ratio (o/e) 0, 90% interval 0 to 1.89. That is too few expected variants to judge how well the gene tolerates losing a copy. Missense variants: 379 observed, 373.95 expected, observed/expected ratio (o/e) 1.01, 90% interval 0.93 to 1.1. Synonymous variants: 151 observed, 136.08 expected, observed/expected ratio (o/e) 1.11, 90% interval 0.97 to 1.27.
Homologues: Orthologues: chimpanzee OR6C1 (97% identical), macaque OR6C1 (95% identical), mouse Or6c1 (85% identical), mouse Or6c1b (84% identical), dog OR6C1 (82% identical), dog OR6C1L (82% identical), rabbit OR6C1 (82% identical), rat Or6c1 (82% identical), dog OR6C1K (81% identical), rat Or6c1i-ps1 (81% identical). Paralogues in human: OR6C3 (74% identical), OR6C75 (70% identical), OR6C76 (68% identical), OR6C74 (67% identical), OR6C70 (65% identical), OR6C4 (64% identical), OR6C65 (64% identical), OR6C2 (64% identical), OR6C6 (62% identical), OR2AP1 (60% identical), OR6C68 (58% identical), OR6M1 (46% identical), and 6 more.